TNF (tumor necrosis factor)
Diseases named in the same sentence as TNF in open-access papers (continued):
Sharing a sentence is not in itself a finding about the gene and the disease.
pneumonitis (37 papers, 2005 to 2025). An inflammatory process affecting the lung parenchyma. "Elevated expression levels of TNF-α and IL-6 have been associated with increased severity in radiation-induced toxicities such as pneumonitis and fibrosis." (PMID 40507362, 2025). "IL-1β and TNF-α are produced by activated macrophages and are associated with airway hyper-responsiveness and pneumonitis." (PMID 33616187, 2021). "This case describes a not well-studied situation, in which a mycophenolate-resistant PD-1 blocker-associated pneumonitis was successfully treated with a TNFα neutralizing antibody." (PMID 30176946, 2018). "Here, we report that upon genetic ablation of Ttp, mouse lungs were more susceptible to radiation-induced inflammation (pneumonitis), which is correlated with increased TNF-α levels." (PMID 28548957, 2017). "This observed difference was driven primarily by endocrine (n = 7) and other irAEs (n = 11) for IL-5; dermatologic (n = 5), enterocolitis (n = 6), and endocrine irAEs for IL-6; and pneumonitis (n = 5) for TNF-α (P < 0.05)." (PMID 39403935, 2024). "Cytokines such as IL-1α, IL-1β, IL-6, and TNF-α are produced in excess and potentiate pathological processes such as pneumonitis and vascular thrombosis." (PMID 35991665, 2022). "During pneumonitis, inflammatory cytokines, such as TNF, IL-1β, and granulocyte-macrophage colony-stimulating factor (GM-CSF) are released, leading to cell apoptosis, tissue necrosis, and micro-vascular dysfunction." (PMID 31426531, 2019). "Cytokines released from damaged lung cells (such as IL-1, IL-6, or TNF-α) attract inflammatory cells to the alveoli and pulmonary interstitium, inducing the acute phase pneumonitis." (PMID 31858307, 2019). "SsRNA stimulation of human leukocytes induced cytokines/chemokines similar to those observed in murine SARS-CoV pneumonitis including IL-1α, IL-1β, IL-6, TNF, CXCL8 (IL-8), CCL2 (MCP-1), CCL3 (MIP-1α), and CCL4 (MIP-1β)." (PMID 23236475, 2012). "This cytokine is known to exert anti-inflammatory effects and its exogenous administration was shown to decrease BALF cell recruitment, macrophage-mediated TNF-a production and lung hydroxyproline content in experimental pneumonitis in mice." (PMID 20444277, 2010). "Genetic variation in TNF and the receptor TNFRSF1B were also associated with increased risk of pneumonitis." (PMID 20811626, 2010). "The mRNAs detected were for cytokines involved in acute inflammation and the fibrosis of pneumonitis: TNF-α/β, IL-6, IFN-β/γ, IL-6, IL-10, IL-1α/β, IL12 and MIF." (PMID 16336675, 2005). "Anti-TNF-α treatment significantly mitigated the severity of ICI-related pneumonitis, suggesting that TNF-α+ T cells may be crucial for the pathogenesis of ICI-related pneumonitis and therapeutic targets for its intervention." (PMID 39247203, 2024). "Conceptually, ICI treatment can induce multiple autoimmune-like diseases in autoimmune-prone individuals and TNF-α+ T cells may be therapeutic targets for intervention of immune-related arthritis and pneumonitis." (PMID 36016934, 2022). "This study was performed to verify the hypothesis that EGFR-TKIs induce pneumonitis by blocking EGFR transactivation by TNF." (PMID 31426531, 2019). "This outcome suggests that in the case of late onset pneumonitis during immune checkpoint blockade, TNFα inhibitors might be preferable compared to classical immunosuppressants, although more studies are needed to confirm this." (PMID 30176946, 2018). "A relationship between TNF-α secretion and apoptosis in the fallopian tube has also been suggested by studies using a mouse model of infection with a Chlamydia trachomatis mouse-specific pneumonitis strain." (PMID 19412525, 2009). "They indicated that other anti-TNFα drugs (including etanercept, adalimumab, certolizumab, and golimumab) could be alternatives to infliximab and that anti-IL-1 therapy (anakinra or canakinumab) might be helpful for patients with severe anti-TNFα-refractory pneumonitis." (PMID 33042827, 2020).
pneumonitis (continued). "Drug-induced pneumonitis can arise from medications used in the treatment of connective tissue diseases (CTD), such as methotrexate, leflunomide, sulfasalazine, tumor necrosis factor-alpha inhibitors, and cyclophosphamide." (PMID 40386698, 2025). "Previous studies have reported that fibrogenic cytokines including CXCL1, CXCL2, TNF-α, and CXCL8 are involved in bleomycin-induced pneumonitis." (PMID 41425704, 2025). "Secondly, Th1-cell subsets were upregulated in ICI pneumonitis, producing large amounts of IFN-γ and TNF-α." (PMID 36944820, 2023). "Several guidelines recommend immunomodulatory agents, such as TNF-α inhibitors, anti-IL-6, and intravenous immunoglobulin (IVIG), as second-line treatment for steroid-refractory ICI-pneumonitis." (PMID 36944820, 2023). "Given the current understanding of bleomycin-induced pneumonitis (BIP), the use of tumor necrosis factor alpha (TNF-α) inhibitors such as infliximab for late-stage disease appears to be of limited benefit." (PMID 30349718, 2018). "Certolizumab, similarly to other TNFα inhibitors, may lead to acute exacerbations in RA-ILD patients, probably via NLRP3 inflammasome activation precipitate pneumonitis." (PMID 37371850, 2023). "The TNF-α inhibitor, infliximab, and the IL-6 inhibitor, tocilizumab, are used as second-line therapies in patients with steroid-refractory irAEs, including ICI-Pneumonitis." (PMID 34675810, 2021). "In addition, the findings of a “sensitizing” effect of TNF-α on the IFN-responsiveness and IP10 induction in HLMVEC, HPASM and A549 cells pose the interesting question of whether underlying inflammatory conditions in the lung could predispose IFN-treated patients to pneumonitis or other ILDs." (PMID 23056449, 2012). "Hyper-elevation of Interleukin1 (IL-1), Tumor necrosis factor-1alfa (TNF-1 alfa), and Interleukin 6 (IL-6) produced by inflammatory macrophage M1 may damage the lung alveoli leading to severe pneumonitis, decreased oxygenation, and potential death despite artificial ventilation." (PMID 32489696, 2020). "Therefore, for cases of EGFR TKI-induced pneumonitis, EGFR tyrosine kinase activity may be required to maintain homeostasis in TNF-rich lung environments where chronic inflammation is present." (PMID 31426531, 2019).
eczema (36 papers, 2005 to 2025). "Compared with TNF inhibitors, IL-23 inhibitors were associated with a lower risk of paradoxical eczema (hazard ratio [HR], 0.39; 95% CI, 0.19-0.81)." (PMID 38055239, 2024). "Compared with TNF inhibitors, IL-23 inhibitor exposure was associated with significantly lower risk of paradoxical eczema; this result may have been attributable mostly to guselkumab due to the low number of exposures to other IL-23 inhibitors in these data." (PMID 38055239, 2024). "TNF-α-blocking therapy down-regulates Th1 immune responses, which might induce a shift of the Th1/Th2 balance towards Th2-dominated immune responses and which might promote an increased susceptibility to atopic disorders, such as eczema." (PMID 15899052, 2005). "TNF-α inhibitors can paradoxically induce eczema, with affected patients showing upregulation of the TNF/IFN-γ signaling pathway." (PMID 40948748, 2025). "Previous studies have demonstrated that matrine and berberine can suppress inflammatory factors such as TNF-α and downregulate key genes in inflammatory pathways, thereby exerting therapeutic effects on eczema." (PMID 40612058, 2025). "In eczema patient studies, TNF-α levels exhibited a gradient: blank and PBS control were lowest, normal skin slightly higher, patient healthy region higher, and patient lesion region highest." (PMID 41302804, 2025). "In eczema, TNF-α, IL-1β, and IL-4 expression increases, binding to receptors activates NF-κB, stimulating inflammatory mediator production (e.g., TNF-α, IL-1β, and IL-4), creating a positive feedback loop." (PMID 40933470, 2025). "Taken together, these results indicate that the clinical strains isolated from human eczema skin have the potential to stimulate TNF-α production by U937 cells and BBR treatment inhibits this ability without any cell cytotoxicity." (PMID 39404402, 2024). "IFN-γ and TNF, for instance, exert pro-apoptotic effects on keratinocytes, which can contribute to eczema formation, cell death and spongiosis." (PMID 38892346, 2024). "Shikonin is the main chemical component of Comfrey; it can act on nine eczema-related targets, among which TNF and PTGS2 are the common targets of shikonin, gallic acid, and ellagic acid." (PMID 35907999, 2022). "Some studies also found that the abundance of Ruminococcaceae decreased in infants with eczema, and inflammatory cytokines such as IL-6 and TNF-α increased, and a decrease in the number of Ruminococcus can induce a toll-like receptor inflammatory response." (PMID 36710970, 2022). "Instead, the levels and expression patterns of these cytokines are changed in eczema skin of both AE and SE compared to skin of HC, showing an altered balance in the eczema skin for these TNF members." (PMID 21765951, 2011). "TNF-α-blocking therapy had already been stopped in 4 patients before the onset of eczema and was continued in 13 patients, of whom 7 had persisting or recurring lesions." (PMID 15899052, 2005). "Huangbo has also become a staple for eczema treatment, as it could decrease mRNA expressions of proinflammatory cytokines (like IL-1β, TNF-α, IL-17, IL-4, and IL-13)." (PMID 41311842, 2025). "Eczema is one of the most common side effects of TNF‐α inhibitors." (PMID 38700458, 2024). "Under the action of allergens in the skin system, numerous inflammation-mediated factors, such as TNF-α, IL1β, and IL-4, are secreted during epidermal keratinization, all of which interact with each other in the pathogenesis of eczema, thus influencing the development and prognosis of the disease." (PMID 35907999, 2022). "Duration of exposure to tumor necrosis factor (TNF) inhibitors, interleukin (IL) 17 inhibitors, IL-12/23 inhibitors, or IL-23 inhibitors until paradoxical eczema onset, treatment discontinuation, last follow-up, or death." (PMID 38055239, 2024).
eczema (continued). "CTGO significantly improved the skin surface and histopathological characteristics of eczema-affected rats, downregulated the expression of IL-4, TLR4, NF-κB (p65), IL-1β, and TNF-α, and upregulated the expression level of IFN-γ." (PMID 35907999, 2022). "It has recently been reported that TWEAK and TNF-α can cooperate in the induction of keratinocyte apoptosis, suggesting a role of TWEAK in eczema formation of AE." (PMID 21765951, 2011). "In the treatment of paradoxical eczema, TNF‐α inhibitors do not need to be discontinued in most cases, and treatment can be continued with topical corticosteroids along with calcineurin inhibitors." (PMID 38700458, 2024). "The serum levels of IL-6, IL-17, and TNF-α are also downregulated through the downregulation of mitogen-activated protein kinase (MAPK) and the NF-κB pathway by treatment with MC-EO in a DNCB-induced eczema mouse model." (PMID 38791435, 2024). "While the incidence of paradoxical eczema was numerically highest among IL-17 inhibitor exposures, it was not significantly different from the incidence among TNF inhibitor exposures." (PMID 38055239, 2024). "Despite the frequent occurrence of eczema in IBD patients treated with anti-TNF-α, no clear recommendations have been made on its management." (PMID 33802483, 2021). "ELISA and Western blotting analyses revealed that SYXL alleviated eczema-like skin lesions induced by DNCB in animal models, reversed histopathological abnormalities, curbed the expression of pro-inflammatory cytokines IL-1β, IL-6, and TNF-α, and inhibited the phosphorylation of JAK2 and STAT3." (PMID 40612058, 2025). "Our molecular docking results showed that the overall scores of TNF, TLR4, IL1β, and Alb when docking with four key components were all lower than –5.0 kcal/mol, which suggested that they may play an essential role in CTGO against eczema." (PMID 35907999, 2022).
hearing loss (36 papers, 2014 to 2025). "Future research should aim to elucidate the mechanistic role of TWEAK in hearing loss using in vivo models, with particular emphasis on investigating the potential of TNF-α and TWEAK/Fn14 inhibitors as therapeutic agents." (PMID 39923035, 2025). "The role of TNF- α as an inflammatory mediator contributing to hearing loss has been well established, with multiple proposed mechanisms linked to hearing loss." (PMID 41041647, 2025). "Our findings broaden the understanding of the beneficial effects of DEX pretreatment on TNF-α-induced ototoxicity and also provide basis for designing therapeutic approaches to treat or prevent inflammatory-related hearing loss." (PMID 37733709, 2023). "The polymorphisms of genes encoding inflammatory mediators such as TNF-α have been reported to contribute to the incremental risk of hearing impairment in elderly Japanese people." (PMID 36158549, 2022). "In noise-induced hearing loss, the damage to fibrocytes of the spiral ligament is likely to lead to changes in cytokines or chemokines such as TNF-a, IL-1b, IL-6, and Icam-1." (PMID 34150778, 2021). "Noise exposure represents the second most common cause of acquired sensorineural hearing loss and we observed that tumor necrosis factor α (TNFα) was involved in this context." (PMID 32294929, 2020). "The use of different anti-TNFα agents, which can act by inhibition of the protein, such as infliximab, or by the decoy receptor, such as etanercept, can mitigate noise-induced hearing loss." (PMID 32294929, 2020). "For vestibular schwannoma-related sensorineural hearing loss, in particular, the TNF-α level within vestibular schwannoma secretions have been reported to be associated with a degree of hearing loss." (PMID 33147893, 2020). "Cumulative evidence has indicated that NF-κB is a key transcription factor driving inflammation and that TNF-α, ROS, and NF-κB are inextricably tied together in inflammation and immunity of noise-induced hearing loss." (PMID 32617095, 2020). "Apoptosis-related hearing loss secondary to long-term exposure to circulating mediators of chronic inflammation including TNF should lead to bilateral SNHL." (PMID 31781229, 2019). "A cohort study of 8,675 Japanese subjects revealed an association between hearing impairment and polymorphisms of genes encoding inflammatory mediators TNF-α and TNF receptor super family 1B." (PMID 31632328, 2019). "The novelty of this observation is that this is the first time TNF-α mediated potentiation of TRPV1 mediated Ca2+ entry has been implicated in hearing loss." (PMID 31632242, 2019). "Previous studies showed that TNF-α levels during acute experimental PM positively correlate with the severity of hearing loss and that a reduction in inflammatory cytokines improved hearing capacity." (PMID 30131074, 2018). "The present observation implied that the signaling cascades of TNF-α were involved in age-related hearing loss." (PMID 25469152, 2014). "Additionally, the up-regulation of TRPV1 following noise exposure is linked to increased levels of the inflammatory cytokine TNF-α, indicating its role in noise-induced hearing loss." (PMID 40688696, 2025). "Moreover, levels of inflammatory mediators such as interleukin-1β, IL-1 receptor antagonist, IL-6, heat shock protein 70, and tumor necrosis factor-α have been shown to correlate closely with hearing loss severity and disease progression." (PMID 41011137, 2025). "The NF-κB signaling cascade plays a central role in inflammation by regulating the release of pro-inflammatory mediators, including inducible nitric oxide synthase (iNOS) and tumor necrosis factor-alpha (TNF-α), which both contribute to cochlear damage and hearing loss." (PMID 40126270, 2025).
hearing loss (continued). "TNF-α is a cytokine with important key functions in various cellular processes, such as the maintenance of cellular homeostasis and the regulation of pro-inflammatory responses and which plays an important role in the inner ear in the context of hearing loss." (PMID 39015324, 2024). "Based on this fact that the inhibition of TNFα was beneficial in noise-induced hearing loss, the blockade of TNFα by gene silencing could putatively provide relevant data to understand the real action of this cytokine in this context, due to gene silencing." (PMID 32294929, 2020). "So far, the exact effector mechanisms underlying sudden and autoimmune hearing loss are unknown, but a recent TNF-α-related study raised the possibility that a potential connection could exist between ROS and these types of hearing losses." (PMID 33147893, 2020). "Thus, noise-induced neuroinflammation (i.e., microglial activation and TNF-α release) is likely a mechanism underlying the shift of excitatory-to-inhibitory synaptic balance following noise exposure and hearing loss." (PMID 31211773, 2019). "Additionally, previous studies have demonstrated that increased ROS production and pro‐inflammatory cytokines, such as TNF‐α, IL‐1β, and IL‐6, play critical roles in cochlear tissue damage, in noise‐ or cisplatin‐induced hearing loss." (PMID 31353811, 2019). "The odds ratios for the hearing impairment (PTABE >25 dB) risk under additive genetic model were significant in TNF-α rs1800630 and TNFRSF1B rs1061624, which were respectively 1.172 (confidence interval [CI]: 1.005-1.367), 1.211 (CI: 1.053-1.392) in model after adjustment for possible confounders." (PMID 25469152, 2014). "Several animal and clinical studies have reported an association between increased levels of TNF-α with hearing loss and the protective effects of TNF-α inhibitors on hearing loss, although it is still controversial whether TNF-α acts as a mediator or is a direct etiology of hearing loss." (PMID 37733709, 2023). "Therefore, the blockade of TNF-α could be an important strategy in prevention and treatment of hearing loss." (PMID 37733709, 2023). "However, the intrinsic molecular mechanism by which TNF-α influences aging individuals’ increased risk of hearing loss remains unclear." (PMID 36158549, 2022). "Therefore, in this study, we aimed to investigate the effect of Tnfα gene silencing on the expression profile related to the TNFα metabolic pathway in an experimental model of noise-induced hearing loss and also to determine the effect of TNFα blockade by gene silencing in the ABR click parameters." (PMID 32294929, 2020). "By promoting the release of cytokines such as IL-1β, IL-6, and TNF-α, and regulate the processes of programmed cell death, the NOD pathway can lead to hearing loss." (PMID 40353062, 2025). "The present population-based cohort study demonstrated that TNF-α rs1800630 and TNFRSF1B rs1061624 contributed to the incremental risk of hearing impairment in the elderly." (PMID 25469152, 2014). "The present population-based cohort study demonstrated that TNF-α rs1800630 and TNFRSF1B rs1061624 contributed to the incremental risk of hearing impairment in the elderly Japanese population." (PMID 25469152, 2014). "Our finding of elevated levels of TNF-α, IL-2R, CD163, eotaxin, and HGF in VS-CM being significantly associated with hearing impairment in patients with VS suggests that inflammatory pathways and immune cell activation are key contributors to VS-induced hearing loss." (PMID 39923035, 2025). "However, our observation that Pak1 gene expression was up-regulated in the cochlea submitted to TNFα blockade gene silencing not only is a novelty finding but also can putatively suggest that its up-regulation may promote cell survival after the noise-induced hearing loss in our experimental model." (PMID 32294929, 2020).